SOD1 (superoxide dismutase 1)
Diseases named in the same sentence as SOD1 in open-access papers (continued):
Sharing a sentence is not in itself a finding about the gene and the disease.
lymph node metastasis (4 papers, 2018 to 2025). "This study investigated whether SOD1 and SOD2 expression in OPC affects primary tumor progression, lymph node metastasis, stage, and overall survival (OS)." (PMID 40244057, 2025).
Myelopathy (4 papers, 2010 to 2021). Myelopathy is an descriptive term, referring to pathology leading to a neurologic deficit related to the spinal cord. "The most clinically relevant animal models of ALS are transgenicmouse overexpressing the mutated SOD1 gene, and a canine model of the disease calleddegenerative myelopathy, which can deliver significant insights into the mechanisms of motorneuron degeneration in ALS." (PMID 31124369, 2019). "Degenerative myelopathy of dogs: inclusions capable ofbinding with SOD1 antibodies are observed in the cytoplasmof neurons; demyelination of the white matter of lateral cordsand axonal loss." (PMID 25926999, 2015).
nasal polyps (4 papers, 2012 to 2024). "Our results indicated that the antioxidant functions of SOD1 and SOD2 in nasal polyps are also regulated by the APA site switching of these genes." (PMID 23185289, 2012). "In contrast, increased SOD1 levels have been described in nasal polyps of nonallergic CRSwNP subjects, reminiscent of SOD1 differences observed in nasal polyps of our RIST-positive and RIST-negative examinees." (PMID 35628331, 2022).
neurotoxicity (4 papers, 2009 to 2022). Toxicity that causes injury to the central or peripheral nervous system or damages its function. "Neurotoxicity in this system thus appears to be mediated by misfolded SOD1 and is exerted on synaptic vesicle biogenesis and/or trafficking." (PMID 19165329, 2009).
osteosarcoma (4 papers, 2018 to 2025). A usually aggressive malignant bone-forming mesenchymal neoplasm, predominantly affecting adolescents and young adults. "We found that SOD1 silencing was an effective method for inducing cell death in ATRX-deficient osteosarcoma cell lines; further, this approach was more effective in ATRX-null HeLa-LT than ATRX-wildtype cells." (PMID 40748226, 2025). "An ALT-negative/telomerase-positive osteosarcoma cell line (MG63) was also tested—this showed that whilst there was some decreased viability in response to silencing of SOD1, the effect was much milder than that observed in ALT-positive osteosarcomas." (PMID 40748226, 2025). "A panel of well characterised ALT-positive osteosarcoma cell lines was subsequently treated with the same shRNA sequences to SOD1." (PMID 40748226, 2025). "Expression of SOD1 is upregulated both in osteosarcomas O-P1 and O-P2, as well as soft tissue and chondrosarcoma samples." (PMID 41300532, 2025). "When treating osteosarcomas, treatment with DHA bFGF in samples O-P1 and O-P2 exerts a stronger influence on SOD1 expression compared to treatments with AA bFGF, while in Ch-P4, L-P5, and Rm-P6, the effect was the opposite." (PMID 41300532, 2025). "Exposure of the archetypal ALT-positive osteosarcoma cell line, U2OS, to H2O2, hypoxia or SOD1 gene silencing resulted in increased APBs, indicating increased ALT-pathway activity." (PMID 39921567, 2025). "In this work, we found that several osteosarcoma lines—such as U2OS, G292 and SAOS2—had varying levels of sensitivity to silencing of SOD1." (PMID 40748226, 2025).
pancreatic adenocarcinoma (4 papers, 2017 to 2024). "We explored the expression of several antioxidants (NRF2, GPX2, SOD1,2) and NRF2 target genes (NQO1, HMOX1, TXN) in 179 tumors and 171 normal tissues from the TCGA/GTEx pancreatic adenocarcinoma (PAAD) dataset." (PMID 38782891, 2024).
Respiratory insufficiency (4 papers, 2020 to 2024). "The time to the clinically relevant endpoints including walking loss, bulbar involvement, respiratory insufficiency and overall survival, were significantly associated with the in silico predictions results including substantial disturbance of SOD1 structure." (PMID 34996976, 2022). "In this regard, various studies suggest that individuals with altered genes such as SOD1 and C9ORF72 have a higher likelihood of developing respiratory insufficiency than those with mutations in other genes related to this disease." (PMID 39585060, 2024).
acute coronary syndrome (3 papers, 2017 to 2024). Signs and symptoms related to acute ischemia of the myocardium secondary to coronary artery disease. "Similarly, interval cycloergometer CR training, five times a week, for a total of 15 training sessions increased TAS, SOD-1, and glutathione peroxidase (GPx) activity in acute coronary syndrome patients, but decreased CAT activity." (PMID 31003426, 2019).
acute hepatitis B (3 papers, 2006 to 2024). "Regarding viruses that cause known hepatic pathology, it has already been demonstrated that Hepatitis B virus infection causes a reduction in the cytoplasmic SOD1 and increased levels of MDA58." (PMID 31653913, 2019).
Airway obstruction (3 papers, 2020 to 2024). Obstruction of conducting airways of the lung. "In PBMCs, we showed that the shifts in expression in both GSR and SOD1, along with increased airway obstruction in favor of CS, can cause extensive systemic and not only localized OS." (PMID 39199199, 2024).
Autoimmunity (3 papers, 2022 to 2025). The occurrence of an immune reaction against the organism's own cells or tissues. "The next three upregulated genes in treated individuals were DNAJB1, which is a part of the HSP40 complex that has been shown to play a role in anti-inflammatory processes in autoimmunity; and RGS1 and SOD1, which are important for antiviral immune responses." (PMID 36175869, 2022).
breast tumor (3 papers, 2014 to 2023). "We see that the levels of SOD1, also an Nrf2 transcriptional target, are decreased in breast tumor cells deficient for Merlin in comparison to their respective controls; while SUM159 Merlin expressors support increased SOD1 levels." (PMID 33410252, 2021). "Next, TCGA database indicated that all mRNAs encoding HO-1, CISD2, SOD-1 and GSR in breast tumors were significantly higher than those in normal tissues." (PMID 37217939, 2023). "Among OS endpoints, excess 8-OHdG and protein carbonyl were reported, along with upregulated total SOD, SOD-1, and EC-SOD in plasma and breast tumours." (PMID 24876913, 2014).
esophageal squamous cell carcinoma (3 papers, 2023 to 2025). Esophageal squamous cell carcinoma (ESCC) is a type of esophageal carcinoma (EC) that can affect any part of the esophagus, but is usually located in the upper or middle third. "CXCL1 also decreases the expression of superoxide dismutase 1 (SOD1) in cancer cells, as shown by experiments on esophageal squamous cell carcinoma cells, which results in increased levels of ROS in the tumor cell and thus increased activity of DNA damage repair enzymes." (PMID 40427171, 2025).
familial disease (3 papers, 2013 to 2019). "Approximately 95–90% of ALS cases are sporadic (sALS) while the balance is genetically linked familial disease (fALS), where mutations in superoxide dismutase 1 (SOD-1) cause 25% of cases." (PMID 25100994, 2014). "In 10% of patients, ALS is a familial disease and 20% of these familial ALS patients contain mutations in the gene encoding superoxide dismutase 1 (SOD1)." (PMID 24368896, 2013).
lymphopenia (3 papers, 2008 to 2025). Reduction in the number of lymphocytes. "Based on diminished T cell responses and observations of profound lymphopenia in G93A-SOD1 Tg mice at end stage, we assessed splenic lymphocyte phenotype and function in early symptomatic (14 weeks old) B6SJL SOD1 Tg mice to detect early immune cell aberrations in spleen." (PMID 18648532, 2008). "Indeed, we demonstrated that spleens of SOD1 Tg mice at end stage display significant reductions in size and weight and profound lymphopenia." (PMID 18648532, 2008). "Previous studies have implicated adaptive immune system dysfunction in ALS patients and mutant SOD1 mice, showing accelerated thymus inactivation or involution, reduced CD4+ T cell number, spleen shrinkage and lymphopenia." (PMID 25889790, 2015). "Transfer of naïve lymphoid cells from Wt donor mice to SOD1 Tg recipient mice failed to affect survival or overcome the observed lymphopenia." (PMID 18648532, 2008).
Menkes disease (3 papers, 2019 to 2025). A usually severe multisystemic disorder of copper metabolism, characterized by progressive neurodegeneration and marked connective tissue anomalies as well as typical sparse abnormal steely hair. "Notably, however, SOD1 aggregates are a key ALS hallmark but are absent in spinal cords from CCS/G93-SOD1 mice, and mortality in these mice may be explained entirely by copper deficiency during the first 10 days of life, in some ways resembling Menke’s disease better than adult-onset ALS." (PMID 31118040, 2019).
neuro-degenerative diseases (3 papers, 2012 to 2014). "The results show, somewhat unexpectedly, that the toxic species of SOD1 in this type of experimental setting is not an aggregate, as typically observed for proteins implicated in other neuro-degenerative diseases, but the folded and fully soluble apo protein." (PMID 22558346, 2012).
neuropathic pain (3 papers, 2020 to 2023). Chronic pain caused by damage to nerve fibers. "All the compounds also had anxiolytic and antidepressant actions, normalized the up-regulation of the NLRP3 inflammasome, and enhanced/normalized the Nrf2, HO-1, and SOD-1 levels in the DRG and AMG of mice with neuropathic pain." (PMID 37891937, 2023).
osteonecrosis (3 papers, 2022 to 2024). A none disease characterized by death of bone tissue due to a lack of blood supply. "In patients with osteonecrosis and X-ray exposure; high values of MDA level (2.999–4.9980) were associated with low levels of SOD (1.4-3.235), CAT (0.0010-0.0644) and GSH (0.0051-0.0097)." (PMID 35720997, 2022).
Primary lateral sclerosis (3 papers, 2022 to 2025). "Although some studies analysed ALS subgroups with isolated upper or lower motor neuron involvement, such as primary lateral sclerosis (PLS), progressive muscular atrophy (PMA), or hereditary motor neuropathies (e.g. SOD1 mutations), the majority lack sufficient data for meaningful comparisons." (PMID 40181571, 2025).
reflux esophagitis (3 papers, 2022 to 2025). "As a result of this experiment, it was confirmed that SC treatment activated the PPARγ/RXR pathway and increased the expression of antioxidant enzymes such as SOD-1 and catalase in reflux esophagitis." (PMID 35027935, 2022).
septic shock (3 papers, 2016 to 2025). Shock caused by infection; frequently caused by gram negative bacteria, although some cases have been caused by other bacteria, viruses, fungi, and protozoa; characterized by fever, chills, tachycardia, tachypnea, and hypotension. "When compared to control subjects, septic shock patients had a higher serum malondialdehyde concentration and lower erythrocyte SOD1 activity." (PMID 27709557, 2016).
skin aging (3 papers, 2022 to 2025). The gradual irreversible changes in structure of skin that occur as a result of the passage of time.. "Although these results were for blood, they support the possibility that SOD3 expression, but not SOD1 and SOD2, is significantly altered with skin aging." (PMID 35624792, 2022).
skin cancer (3 papers, 2021 to 2025). "Although the impact of oxidative stress and inflammation on skin cancer has been extensively documented, no studies have specifically examined SOD1 and iNOS expression in the CFC." (PMID 38891963, 2024).
viral hepatitis (3 papers, 2008 to 2025). An acute or chronic inflammation of the liver parenchyma caused by viruses. "Using a mouse model of viral hepatitis, we identified virus-induced early transcriptional changes in the redox pathways in the liver, including downregulation of superoxide dismutase 1 (Sod1)." (PMID 26588782, 2015). "Bergthaler and colleagues show that superoxide dismutase 1 protects the liver from type I interferon-driven oxidative damage in viral hepatitis." (PMID 26588782, 2015). "To investigate whether SOD enzymes contribute to viral hepatitis, we infected Sod1−/−, Sod2+/−—a commonly used model for Sod2 deficiency —and Sod3−/− mice with LCMV and monitored the course of disease." (PMID 26588782, 2015). "Together, our results indicate that SOD1 plays a non-redundant protective role in viral hepatitis and liver damage." (PMID 26588782, 2015).
acute myeloid leukemia (2 papers, 2023 to 2024). Acute myeloid leukemia (AML) is a group of neoplasms arising from precursor cells committed to the myeloid cell-line differentiation. "To validate the essentiality of SOD1 in PPM1D-mutant cells, we performed in vitro competitive proliferation assays in two different acute myeloid leukemia (AML) cell lines, OCI-AML2 and OCI-AML3." (PMID 38896450, 2024).
aspergillosis (2 papers, 2024). Aspergillosis is an infection, growth, or allergic response caused by the Aspergillus fungus. "Triple deletion of sod1, sod2, and sod3 genes did not decrease the virulence of A. fumigatus in an immunocompromised murine aspergillosis model; however this triple mutant exhibited increased sensitivity to killing by alveolar macrophages of immunocompetent mice." (PMID 39728319, 2024).
axonal neuropathy (2 papers, 2023 to 2025). Any nerve disorder affecting the axon of a nerve. "In the case described by Nyshiyama (patient 2), a SOD1 L8V mutation was found, with an exceptionally long disease duration, the patient being alive at least 10 years after probable ALS onset and 14 years after possible axonal neuropathy onset." (PMID 37610446, 2023). "This emphasizes the importance of including SOD1 analysis in genetic testing for IPN, particularly in patients showing asymmetric, length-dependent axonal neuropathy, as noted in both clinical and electrophysiological findings." (PMID 39932579, 2025). "This study reveals the clinical variability and likely underdiagnosis of SOD1-IPN, supporting the integration of SOD1 screening in IPN genetic testing, especially for patients with asymmetric, length-dependent axonal neuropathy evident in clinical and electrophysiological assessments." (PMID 39932579, 2025).
cardiac arrest (2 papers, 2014 to 2023). Cessation of breathing and/or cardiac function. "Faster recovery of cerebral perfusion was observed in SOD1-overexpressed rats after cardiac arrest and resuscitation." (PMID 24949080, 2014).
Chorea (2 papers, 2012 to 2022). Chorea (Greek for 'dance') refers to widespread arrhythmic involuntary movements of a forcible, jerky and restless fashion.
colorectal tumor (2 papers, 2019 to 2021). "The expression of SOD2 is increased in pre-malignant (T and N) stages during colorectal carcinogenesis whereas SOD1 is expressed only in colorectal tumors." (PMID 31623294, 2019).
congenital myasthenia (2 papers, 2018 to 2024). "Consistent with this idea, adenoviral expression of Dok-7, an inside-outside activator of MuSK, not only extends longevity of SOD1-G93A mice but also provides benefit in other mouse models of neuromuscular disease, including congenital myasthenia and Emery-Dreifuss muscular dystrophy." (PMID 29460776, 2018).
corneal ulcer (2 papers, 2012 to 2015). Area of epithelial tissue loss from corneal surface; associated with inflammatory cells in the cornea and anterior chamber. "So far, SOD1 entrapped in liposomes was previously shown to be effective in the treatment of noninfectious corneal ulcers." (PMID 26697135, 2015).
distal hereditary motor neuropathies (2 papers, 2013 to 2022). "Here we show that the molecular chaperone, HSJ1 (DNAJB2), mutations in which cause distal hereditary motor neuropathy, can reduce mutant SOD1 aggregation and improve motor neuron survival in mutant SOD1 models of ALS." (PMID 24023695, 2013).
fungal keratitis (2 papers, 2017 to 2023). "Interestingly, the antioxidant enzyme superoxide dismutase-1 (SOD1) was strongly produced in normal and mock control corneas, but its levels decreased significantly in fungal keratitis." (PMID 28874754, 2017).
gastric adenocarcinoma (2 papers, 2021 to 2026). "To verify the in vitro inhibition by the LPE of key redox enzymes (CAT, SOD-1/2, and MAO-A) in the gastric adenocarcinoma cells, we assessed changes in the protein expression of these enzymes after LPE treatment." (PMID 41596250, 2026).
hepatoblastoma (2 papers, 2023 to 2025). Hepatoblastoma (HB) is a malignant hepatic tumor and is the most common pediatric liver cancer. "Next, we examined the changes in proliferation and apoptosis of hepatoblastoma cells after inhibition of SOD1 with LCS-1." (PMID 37256172, 2023). "In this study, we confirmed that DHM inhibited the growth of hepatoblastoma cells and induced apoptosis through down-regulation of ROS by targeting SOD1." (PMID 37256172, 2023). "At the same time, inhibition of SOD1 weakened the inhibitory effect of DHM on hepatoblastoma." (PMID 37256172, 2023).
homocystinuria (2 papers, 2013 to 2019). An autosomal recessive inherited metabolic disorder caused by mutations in the CBS, MTHFR, MTR, and MTRR genes. "Although the cytotoxicity of extracellular SOD1 may represent a plausible mechanism of pathogenesis in disorders characterized by high concentrations of extracellular thiols (e.g., in homocystinuria, where plasma Hcy may reach 500 μM71), it is unlikely the pathogenic mechanism in ALS." (PMID 31346243, 2019).
hypovitaminosis D (2 papers, 2024 to 2025). "According to our results, hypovitaminosis D (independently of BMI status) was associated only with increased adiponectin levels and not with other biomarkers of inflammation and oxidative stress (WBC counts, CRP, MCP-1, MPO, I-TAC, SOD-1)." (PMID 39408928, 2024).
intestinal cancer (2 papers, 2023 to 2024). "They found that under hypoxia conditions, SOD1 levels drop, which translates into conditions in intestinal cancer tumors caused by rapid proliferation and less oxygen access to tumor cells." (PMID 39195258, 2024).
ischemic cardiomyopathy (2 papers, 2012 to 2025). Ischemic cardiomyopathy is a cardiomyopathy in which a weakness in the muscle of the heart due to inadequate oxygen delivery to the myocardium with coronary artery disease being the most common cause. "First, SOD1 was shown to be one of the PDI molecular targets in ischemic cardiomyopathy." (PMID 23061969, 2012).
Kennedy disease (2 papers, 2010 to 2021). Kennedy's disease, also known as bulbospinal muscular atrophy (BSMA), is a rare X-linked recessive motor neuron disease characterized by proximal and bulbar muscle wasting. "Granular inclusions were also found in carriers of SOD1 mutations and in spinobulbar muscular atrophy (SBMA) patients and they were the major type of inclusion detected in ALS patients homozygous for the wild type-like D90A mutation." (PMID 20644736, 2010).
optic neuropathies (2 papers, 2022 to 2025). "Nrf2 levels were also elevated by erinacine A in the retina and optic nerve of rats following traumatic optic neuropathy, and it was proposed that activation of the Nrf2/HO-1/SOD1 antioxidative stress pathway led to reduced inflammation and apoptosis (Hsu C.-L." (PMID 40626304, 2025).
progressive supranuclear palsy (2 papers, 2018 to 2019). A rare late-onset neurodegenerative disease characterized by supranuclear gaze palsy, postural instability, progressive rigidity, and mild dementia. "CSF from a subset of PD and progressive supranuclear palsy (PSP) cases was also found to contain the misfolded SOD1, albeit with smaller amounts." (PMID 31744522, 2019).